HCG4 (HLA complex group 4)
Synonyms: HCGIV-10; HCGIV.9; formerly HCG4P10
Gene: Transcribed unprocessed pseudogene on chromosome 6 (29,791,753 to 29,792,750, reverse strand). Ensembl gene ENSG00000176998.
Diseases named in the same sentence as HCG4 in open-access papers:
HCG4 is named in the same sentence as 7 diseases in open-access papers, as found by Europe PMC text mining. Sharing a sentence is not in itself a finding about the gene and the disease. The quoted sentences say what the papers report.
preeclampsia (2 papers, 2022 to 2025). Preeclampsia is a hypertensive disorder of pregnancy that is characterized by new-onset hypertension with proteinuria presenting after 20 weeks of gestation, and depending on mild or severe forms may initially present with severe headache, visual disturbances, and hyperreflexia. "ZNF311 and HCG4 have been previously associated with rheumatoid arthritis and preeclampsia, conditions that are known to be associated with a higher prevalence of insulin resistance compared to the general population." (PMID 40719081, 2025). "The present study uncovered the downregulation of LOC101927355, LINC00551, PART1, and NRAD1 and the upregulation of HCG4 in the preeclampsia placentas." (PMID 35740273, 2022). "In the case of the lncRNAs UCA1 and HCG4, their expression was upregulated in the preeclampsia placentas (p = 0.035 and p = 0.012, respectively) compared to the control group." (PMID 35740273, 2022). "Six lncRNAs were validated and differentially expressed (p < 0.05) in the preeclampsia and control placentas: UCA1 and HCG4 were found upregulated, and LOC101927355, LINC00551, PART1, and NRAD1 downregulated." (PMID 35740273, 2022). "HCG4 and LOC101927355 lncRNAs could be worthy of further research when seeking novel biomarkers for predicting and monitoring the onset of preeclampsia at the early stages of pregnancy." (PMID 35740273, 2022).
laryngeal carcinoma (1 paper, 2022). Carcinoma that arises from the laryngeal epithelium. "The human leukocyte antigen complex group 4 (HCG4) lncRNA is associated with the recurrence of laryngeal cancer." (PMID 35740273, 2022).
viral infections (1 paper, 2023). "FISH with probes specific for HCG4 was performed, and the results confirmed increased HCG4 expression in the cytoplasm at 24 h.p.i. upon NS1 mutant virus infection." (PMID 38274760, 2023). "Then, we determined the trends in HCG4 expression changes during NS1 mutant virus infection over time by qRT-PCR, and the results showed marked upregulation from 12 h.p.i. onward." (PMID 38274760, 2023). "Subsequently, we investigated the K63-linked ubiquitination of RIG-I upon NS1 mutant virus infection in the absence of HCG4." (PMID 38274760, 2023). "Furthermore, the level of RIG-I ubiquitination decreased upon NS1 S42P mutant virus infection in HCG4 knockdown cells." (PMID 38274760, 2023). "Taken together, our findings demonstrate that HCG4 modulates the innate immune response to SIV infection through K63-linked RIG-I ubiquitination, providing insights into the role of lncRNAs in controlling viral infections." (PMID 38274760, 2023).
cancer (2 papers, 2021 to 2025). A tumor composed of atypical neoplastic, often pleomorphic cells that invade other tissues. "By analyzing data from the Cancer Genome Atlas and other databases, they constructed a competing endogenous RNA (ceRNA) network, revealing key interactions such as HCG4-miR-33b and HOTAIR-miR-1-MAGEA2, which could be linked to recurrence mechanisms." (PMID 40299445, 2025). "HCG4P3 is also known as HLA complex group 4 pseudogene 3, and there is to our knowledge no record of this gene being involved in cancer." (PMID 33461604, 2021).
infection (1 paper, 2023). The state of being infected such as from the introduction of a foreign agent such as serum, vaccine, antigenic substance or organism. "Here, by lncRNA-seq, a total of 153 differentially expressed lncRNAs were identified, and the lncRNA HCG4 was selected due to its significantly higher expression after infection with the NS1 S42P mutant virus." (PMID 38274760, 2023). "In HCG4 overexpressed cells, SH/2014 infection increased the expression of RIG-I, p-IRF3, and p-STAT1/2, and the IFN-β level was also significantly increased compared to that in the control cells." (PMID 38274760, 2023). "In conclusion, our findings suggested that lncRNA HCG4 significantly elevated after SIV NS1 mutant infection, and this is the first study to describe the role of lncRNA HCG4 for NS1 function in SIV infection." (PMID 38274760, 2023). "RSH/2014 NS1 S42P infection promoted RIG-I K63-linked ubiquitination compared to rSH/2014, and then when cells were transfected with HCG4, the ubiquitination levels of RIG-I began to rise in cells infected with rSH/2014." (PMID 38274760, 2023). "We found that the lncRNA HCG4 was markedly upregulated by NS1 mutant infection." (PMID 38274760, 2023). "The RNA-seq results showed that MAPT-IT and HCG4 were the most significantly changed host lncRNAs at 24 h.p.i. with SIV NS1 mutant infection, as they were showed higher level in the rSH/2014 NS1 S42P infection group than that in the rSH/2014 infection group (p < 0.01)." (PMID 38274760, 2023). "The results showed that the K63-linked ubiquitination level of RIG-I in cells was at a high level similar to infection with NS1 mutant virus rSH/2014 NS1 S42P, but it decreased in HCG4 knockdown cells." (PMID 38274760, 2023). "In this study, we demonstrate the antiviral role of the lncRNA HCG4, one of the most highly induced lncRNAs after NS1 mutant infection." (PMID 38274760, 2023).
HCG4 also shares sentences with these, for which no sentence is quoted: Insulin resistance (1 paper); rheumatoid arthritis (1).